CHIC2 (cysteine rich hydrophobic domain 2)
Synonyms: BTL
Tractability: Antibody: UniProt places it where antibodies can reach, with high confidence; its Gene Ontology location is reachable by antibodies, with high confidence; the Human Protein Atlas places it where antibodies can reach. PROTAC: ubiquitination databases record sites on it; its protein half-life has been measured.
Gene: Protein-coding gene on chromosome 4 (53,994,803 to 54,064,605, reverse strand). Ensembl gene ENSG00000109220.
Subcellular location: Cell membrane; Cytoplasmic vesicle
Subcellular location (Human Protein Atlas): Plasma membrane; Vesicles
Gene Ontology:
Molecular function: protein binding
Cellular component: plasma membrane; Golgi-associated vesicle; cytoplasmic vesicle; Golgi apparatus
Genetic constraint (gnomAD): Loss-of-function variants: 9 observed, 20.5 expected, observed/expected ratio (o/e) 0.44, 90% interval 0.26 to 0.77. The upper end of that interval is the gene's LOEUF score, 0.77, which puts it in group 3 of 6, group 1 being the genes least tolerant of losing a copy. Missense variants: 119 observed, 169.34 expected, observed/expected ratio (o/e) 0.7, 90% interval 0.61 to 0.82. Synonymous variants: 59 observed, 59.34 expected, observed/expected ratio (o/e) 0.99, 90% interval 0.81 to 1.24.
Homologues: Orthologues: chimpanzee CHIC2 (100% identical), pig CHIC2 (100% identical), guinea pig CHIC2 (99% identical), mouse Chic2 (99% identical), tropical clawed frog chic2 (96% identical), rat Chic2 (93% identical), zebrafish chic2 (93% identical), dog CHIC2 (90% identical), rabbit CHIC2 (67% identical), Drosophila melanogaster CG5938 (64% identical), Caenorhabditis elegans tag-266 (48% identical). Paralogues in human: CHIC1 (82% identical).
Diseases named in the same sentence as CHIC2 in open-access papers:
CHIC2 is named in the same sentence as 11 diseases in open-access papers, as found by Europe PMC text mining. Sharing a sentence is not in itself a finding about the gene and the disease. The quoted sentences say what the papers report.
glioma (2 papers, 2022 to 2023). A benign or malignant brain and spinal cord tumor that arises from glial cells (astrocytes, oligodendrocytes, ependymal cells). "However, the expression and prognosis of KIT, CHIC2, EXOC1, IGFBP7, RASL11B or USP46 in glioma are unclear." (PMID 36043552, 2023).
eosinophilia (1 paper, 2013). "In the presence of peripheral blood eosinophilia (> 1500 cells/ml), investigation of the CHIC-2 deletion and FIP1L1-PDGFRA rearrangement by means of fluorescence in situ hybridization or the reverse transcriptase polymerase chain reaction is indicated." (PMID 24141298, 2013).
migraine (1 paper, 2022). "Lastly, our scan for inferring causality identified five blood proteins (DKK1, PDGFB, GSTA4, FARS2 and CHIC2) with a significant genetic causality on migraine." (PMID 35546551, 2022). "We show that higher levels of DKK1 and PDGFB, and lower levels of FARS2, GSTA4 and CHIC2 proteins have a significant causal effect on migraine." (PMID 35546551, 2022). "In addition, we identified that higher levels of DKK1 and PDGFB, and lower levels of FARS2, GSTA4 and CHIC2 causally increase the risk of migraine." (PMID 35546551, 2022). "Additionally, our LCV analyses found a significant genetic causality on migraine for lower levels of three blood proteins, including FARS2, GSTA4 and CHIC2." (PMID 35546551, 2022).
cancer (3 papers, 2010 to 2022). A tumor composed of atypical neoplastic, often pleomorphic cells that invade other tissues. "STUB1 and CHIC2 dependency scores also correlated across cell lines in the Cancer Dependency Map, suggesting that this complex may have wide ranging effects on multiple receptors." (PMID 36108743, 2022). "Notably, cases of acute myeloid leukemia with a CHIC2-ETV6 fusion gene have been reported indicating a possible role of CHIC2 in cancer." (PMID 20686603, 2010). "In this study, we used genetics screens, analysis of the Cancer Dependency Map, and IP/MS to discover a mechanism of CSF2RB regulation by a STUB1/CHIC2 complex." (PMID 36108743, 2022).
CHIC2 also shares sentences with these, for which no sentence is quoted: tumor (5 papers); myeloid malignancies (2); chronic eosinophilic leukemia (1); ganglioglioma (1); kidney cancer (1); leukaemia (1); renal carcinoma (1).